NCR2 (natural cytotoxicity triggering receptor 2)
Description:
Cytotoxicity-activating receptor that may contribute to the increased efficiency of activated natural killer (NK) cells to mediate tumor cell lysis.
Synonyms: NK-p44; NKp44; CD336; LY95; dJ149M18.1
Tractability: Antibody: UniProt places it where antibodies can reach, with high confidence; its Gene Ontology location is reachable by antibodies, with high confidence; UniProt predicts a signal peptide or a membrane-spanning region.
Gene: Protein-coding gene on chromosome 6 (41,335,608 to 41,350,889, forward strand). Ensembl gene ENSG00000096264.
Subcellular location: Cell membrane
Pathways (Reactome):
Immune System: DAP12 interactions; Immunoregulatory interactions between a Lymphoid and a non-Lymphoid cell
Gene Ontology:
Molecular function: protein binding; signaling receptor activity; transmembrane signaling receptor activity
Biological process: cellular defense response; signal transduction
Cellular component: cell surface; plasma membrane
Genetic constraint (gnomAD): Loss-of-function variants: 31 observed, 28.41 expected, observed/expected ratio (o/e) 1.09, 90% interval 0.82 to 1.47. The upper end of that interval is the gene's LOEUF score, 1.47, which puts it in group 6 of 6, group 1 being the genes least tolerant of losing a copy. Missense variants: 267 observed, 290.91 expected, observed/expected ratio (o/e) 0.92, 90% interval 0.83 to 1.02. Synonymous variants: 127 observed, 122.44 expected, observed/expected ratio (o/e) 1.04, 90% interval 0.9 to 1.2.
Homologues: Orthologues: chimpanzee NCR2 (97% identical), macaque NCR2 (90% identical), tropical clawed frog trem2 (17% identical). Paralogues in human: TREML4 (28% identical), TREML2 (20% identical).
Diseases named in the same sentence as NCR2 in open-access papers:
NCR2 is named in the same sentence as 72 diseases in open-access papers, as found by Europe PMC text mining. Sharing a sentence is not in itself a finding about the gene and the disease. The quoted sentences say what the papers report.
melanoma (30 papers, 2009 to 2025). A malignant, usually aggressive tumor composed of atypical, neoplastic melanocytes. "Subsequent challenge of these transgenic mice with a mouse melanoma line transduced with human PDGF-DD demonstrated that the NCR2-Tg mice could partially resist tumor challenge and these anti-tumor effects could be partially abrogated by blocking antibodies to NKp44." (PMID 30086799, 2018).
viral infection (8 papers, 2014 to 2025). "It has been suggested that NCR expression may promote the rapid response to pathogens in a non-antigen-specific manner, and we and others have shown that NCR2 is important to the recognition and elimination of certain bacterial and viral infections." (PMID 29085357, 2017).
COVID-19 (7 papers, 2021 to 2025). A disease caused by infection with severe acute respiratory syndrome coronavirus 2. "The selective expression of the splice variants of NCR2 is remarkably associated with infection, suggesting an important role of NCR2 in COVID-19." (PMID 35928229, 2022). "Some features such as IFI44L in B cells, S100A8 in monocytes, and NCR2 in natural killer cells are involved in the innate immune response of COVID-19." (PMID 35928229, 2022). "In their study, IFI44L in B cells, S100A8 in monocytes, and NCR2 in natural killer cells were identified as crucial markers that are involved in the innate immune response of COVID-19, while it was also demonstrated that ZFP36L2 in CD4+ T cells can regulate the inflammatory process of COVID-19." (PMID 40163554, 2025).
glioblastoma (5 papers, 2018 to 2023). The most malignant astrocytic tumor (WHO grade IV). "Finally, examining The Cancer Genome Atlas or TCGA, PDGF-D was observed in multiple human tumors and the presence of NCR2- activated gene expression “signatures” correlated with superior outcome in glioblastoma but not other cancers." (PMID 30086799, 2018).
breast carcinoma (4 papers, 2015 to 2023). "Flow cytometric analysis of NCRs revealed that NCR2 is expressed on NK cells from breast cancer patients possibly induced by the interaction with cancer cells." (PMID 28145491, 2017). "Surface expression of NCR2 was detected in NK cells from breast cancer patients (P = 0.0384)." (PMID 28145491, 2017). "Here, we also show that NCR2 is expressed on NK cells from breast cancer patients." (PMID 28145491, 2017). "We analysed the expression of the NCRs, NCR1, NCR2, and NCR3 in NK cells from breast cancer patients and healthy donors using flow cytometry." (PMID 28145491, 2017). "Therefore, whether expression of NCR2 on NK cells from breast cancer patients would impact NK cell activation negatively or positively depends on the expression of inhibiting (PCNA) versus activating (NKp44L) cellular ligands on breast cancer cells." (PMID 28145491, 2017).
colon carcinoma (3 papers, 2013 to 2021). "In parallel, we assessed the expression levels of NCR2-ligands by staining different tumor cell lines with a NCR2/NKp44-Fc molecule and detected significant ligand expression on several tumor lines (MDA-MB-435, HeLa, and DU-145) while the colon carcinoma line Colo205 showed no significant staining." (PMID 29085357, 2017).
encephalitis (3 papers, 2016 to 2025). An acute inflammatory process affecting the brain parenchyma. "Immune-related genes such as mitochondrial antiviral-signaling protein (MAVS), natural cytotoxicity triggering receptor 2 (NCR2), and IL-10 seem to be involved in the WNV onset of encephalitis." (PMID 40266979, 2025).
chronic periodontitis (2 papers, 2019 to 2021). A chronic inflammatory process that affects the tissues that surround and support the teeth. "For example, NCR2 is associated with chronic periodontitis in pregnant women and NCR3 is associated with susceptibility to cold sores and shingles." (PMID 31134055, 2019). "Interestingly, NCR2, but not NCR1, is associated with chronic periodontitis in humans, which could reflect cross-talk in NCR signaling." (PMID 31134055, 2019).
Sepsis (1 paper, 2021). Sepsis is defined as life-threatening organ dysfunction caused by a dysregulated host response to infection. "In the GSE66099 control and sepsis groups, NCF2 (neutrophil cytosolic factor 2), NLRP12 (NLR family pyrin domain-containing 12), and NCR2 (natural cytotoxicity-triggering receptor 2) had degree 26, 26, and 34, respectively." (PMID 33667236, 2021).
tumor (170 papers, 2007 to 2025). "Remarkably, the upregulation of PDGF-DD-induced NK cell cytokines and chemokines and the downregulation of tumor cell cycle genes correlated with NCR2 expression and was associated with greater survival in a cohort of glioblastoma patients." (PMID 31134055, 2019). "Compared to the BLCA tumour-adjacent normal tissues, tumour expression of transcripts encoding CD2, KLRK1, and NCR2 were higher." (PMID 39877370, 2024). "Human NK cells additionally express and rely on NKp30 (NCR3) and NKp44 (NCR2) for tumor surveillance." (PMID 32290478, 2020). "NCR2 is involved in tumor recognition and can mediate cytokine and cytotoxic granule secretion, but some of its isoforms (such as Nkp44-1) bear an ITIM and can dampen NK cell function." (PMID 29085357, 2017). "Knowledge of the molecular nature of tumour-associated NCR ligands in general and NCR2 specifically is still scarce." (PMID 28145491, 2017). "Before PCNA was described as a ligand for NCR2, it was already reported that its expression inhibits the killing of tumour target cells by NK cells." (PMID 28145491, 2017). "NKp44, which is encoded by the NCR2 gene and expressed on activated natural killer (NK) cells, innate lymphoid cells, and gamma/delta T cells, recognizes PDGF-DD and triggersthe secretion of IFN-γ and TNF-α, which induce tumor cell growth arrest." (PMID 33076479, 2020). "However, experimental studies of CD244, NCR1, and NCR2 showed that knocking them down in NK cells affected tumor surveillance or metastasis (eTable 6 in the Supplement)." (PMID 31483464, 2019). "NKp44 or NCR2 was initially characterized as an induced cell surface receptor on activated human NK cells (mice completely lack NKp44) which augmented cytolytic killing of tumor cells in vitro." (PMID 30086799, 2018). "We detected multiple NK cell family receptor encoding genes (e.g., KLRK1, NCR2, CD2, and CD160) which might be critical in mediating anti-tumour immune responses against BLCA because higher expression of these genes was associated with better patient survival probabilities." (PMID 39877370, 2024). "PGE2 inhibits NK cell effector receptors, such as NCR2/NKp44, NCR1/NKp46, NCR3/NKp30, NKG2D, and CD16, leading to impaired function and promoting tumor immune evasion." (PMID 39609700, 2024). "Activating cytotoxicity receptors (NCRs), NKp46 (NCR1, CD335), NKp44 (NCR2, CD336), NKp30 (NCR3, CD337), contain immunoglobulin-like domains binding to tumor antigens, viral proteins, and some bacterial components." (PMID 34017328, 2021). "Among others, germline-encoded activating receptors, such as KLRK1 (also known as NKG2D) and the Natural cytotoxicity receptors (NCRs), such as NKp46 (NCR1), NKp44 (NCR2), and NKp30 (NCR3), can synergize to overcome inhibitory thresholds and evoke NK cell anti-tumor functions." (PMID 34539622, 2021). "Remarkably, NKp44/PDGF-DD interaction promotes the secretion of IFN-γ and TNF-α by IL-2-activated NK cells, but not cytotoxicity, limiting tumor cell growth in vitro and tumor spread in a transgenic NCR2 mouse model." (PMID 35757695, 2022).
cancer (53 papers, 2008 to 2025). A tumor composed of atypical neoplastic, often pleomorphic cells that invade other tissues. "Studies have shown that in cancers, the levels of activating receptors (NCR1, NCR2, NCR3) are decreased, and this finding has been linked to poor prognosis." (PMID 38628992, 2024). "We and others had previously shown that PCNA expression can be utilized by cancer cells to suppress NK cell activity, through interaction with the NK receptor NCR2/NKp44." (PMID 27102296, 2016). "NCR2 alone differentiated high- from low-grade cancer at multiple CGs." (PMID 31779677, 2019). "PCNA can be recognized by NKp44 protein (natural cytotoxicity triggering receptor 2; NCR2), leading to inhibition of natural killer (NK) cell’s activity against cancer cells." (PMID 36430528, 2022). "NK cells effectively inhibit the function of cancer cells through activation of killer cell lectin like receptor K1 (KLRK1) and natural cytotoxicity triggering receptors 1 and 2 (NCR1 and NCR2)." (PMID 33276627, 2020).
infection (18 papers, 2008 to 2025). The state of being infected such as from the introduction of a foreign agent such as serum, vaccine, antigenic substance or organism. "The selective expression of splice variants of NCR2 is significantly associated with infection." (PMID 35928229, 2022).
NCR2 also shares sentences with these, for which no sentence is quoted: psoriasis (10 papers); influenza (9); acute myeloid leukemia (8); Crohn disease (6); multiple myeloma (6); colorectal cancer (5); HIV-1 infection (5); leukemia (5); autoimmune disease (4); inflammatory bowel disease (4); lung carcinoma (4); pancreatic cancer (4); acute lymphoblastic leukemia (2); AIDS (2); celiac disease (2); gastric cancer (2); glioma (2); graft versus host disease (2); Liver Fibrosis (2); neuroblastoma (2); non-small cell lung carcinoma (2); oral cancer (2); preeclampsia (2); sarcoma (2); thyroid cancer (2); abortion (1); adenoma (1); asthma (1); brain tumors (1); cervical cancer (1).
A further 30 diseases each share a sentence with NCR2 in 1 paper.